CCND1 (cyclin D1)
Diseases named in the same sentence as CCND1 in open-access papers (continued):
Sharing a sentence is not in itself a finding about the gene and the disease.
breast cancer (continued). "Consistently, prior research discovered that EZH2 knockdown resulted in repression of cell proliferation and cell cycle entry in breast cancer, accompanied by a decline in cyclin D1 expression." (PMID 35668081, 2022). "Contradicting results were also found for cyclin D1 function, even though the same breast cancer cell line was used." (PMID 35945910, 2022). "We also found EGFR, MYCN, and MYC in brain cancers;39,40BCL2, MYC, and the loci of IGH translocations in lymph-nodes cancer;41–43CDK12 in breast cancer; CCND1 in liver cancer; and RUNX1, GATA6, and PDE4D in esophageal cancer." (PMID 36163358, 2022). "This chromosomal region is amplified simultaneously with the 11q12–14 region, which contains other oncogenes with a role in breast cancer progression, like CCND1, FGF3, FGF4 and FGF19." (PMID 35193394, 2022). "Inactivation of SREBP1 in human MCF7 breast cancer cells also reduced the expression of cyclin D1 protein." (PMID 36091143, 2022). "Approximately 50% of human mammary carcinomas express abnormally high levels of CYCLIN D1 that are maintained throughout subsequent stages of breast cancer progression from in situ carcinoma to invasive carcinomas." (PMID 36051751, 2022). "This feature has been a long-standing and enigmatic paradox in breast cancer; how can high expression levels of Cyclin D1 in ILC be united with a low to intermediate grade breast cancer type?" (PMID 35437308, 2022). "SETDB1 enhances c-MYC and cyclin D1 expression, and thus provides a growth advantage to breast cancer cells." (PMID 35395812, 2022). "We found that decreased expression of circ_6014 decreased the protein expression levels of PCNA, CDK2/CCNE1, and CDK4/6/CCND1, and overexpression of circ_6014 increased the expression of these proteins in breast cancer cells (Student’s t test, p < 0.05)." (PMID 35383130, 2022). "In contrast, enhanced apoptosis in response to radiation was reported in cyclin D1-overexpressing breast cancer cells." (PMID 36072388, 2022). "In preclinical experiments, abemaciclib is a potent, selective cell growth inhibitor, inhibiting preferentially the CDK4/Cyclin D1 complex and leading to cell senescence and cell death in breast cancer cell lines with broad molecular profiles." (PMID 35813283, 2022). "Many studies have pointed out that cyclin D1 is overexpressed in more than 50% of breast cancers, and the amplification of the Cyclin D1 gene is related to poor prognosis of patients." (PMID 35155248, 2022). "In breast cancer cells, PARP1 competes with histone H1 to maintain transcription of the oncogene CCND1 (encoding cyclin D1), and also acts as a transcriptional coactivator of GATA binding protein 3 (GATA3), thus promoting the transcription of CCND1." (PMID 36566215, 2022). "It is found in endocrine therapy-resistant breast cancer cells, as Cyclin D1 (CCND1) and CDK4 become the target genes of Estrogen and Progesterone." (PMID 36519010, 2022). "In ErbB2-induced mammary tumorigenesis, Ink4a/Arf+/− mice showed decreased p16INK4a, increased Ki-67 expression, increased cyclin D1 protein but decreased mammary tumor apoptosis." (PMID 36358806, 2022). "There was one small clinical trial in which breast cancer patients received limonene for a short period of time; limonene decreased cell cycle regulatory protein expression, including cyclin D1 in breast cancer patients." (PMID 36291926, 2022). "SETDB1 also enhances the protein expression of c-MYC and CCND1 to promote breast cancer cell cycle progression." (PMID 35372573, 2022).
breast cancer (continued). "Since estrogens preferentially induce cyclin D1 to trigger breast cancer proliferation while p21 is transciptionally regulated by ERRα to remove constraints on tumor progression, we evaluated the effect of ERRα on the expression of such targets." (PMID 34003583, 2022). "Among them were major regulators of breast cancer cell proliferation, including CCND1, LEF1, KLF9, GREB1, or MAP3K3." (PMID 36076907, 2022). "Inhibition of CDK4/6 promotes the activation of AKT signalling in breast cancer cells, which results in cyclin D1 accumulation." (PMID 36042494, 2022). "TCF7L2 has been detected on the promoter of the cyclin D1 gene in human breast cancer cells, indicating that it increases cyclin D1 expression." (PMID 36476410, 2022). "Simultaneously, the synthesis of Cyclin D1 is reduced, and the proliferation and metastasis of breast cancer cells are inhibited by MNK inhibitors." (PMID 36052258, 2022). "Cyclin-D1 was overexpressed in 50% of breast cancer cases, so it is elicited to be one of the molecular driving forces." (PMID 36559161, 2022). "Lastly, ESR2 (ERβ gene) expression was negatively correlated with ESR1 (ERα gene) and CCND1 RNA expression in human metastatic ERα+/HER2- breast cancer samples." (PMID 35574319, 2022). "There has been a substantial evidence that CCND1 involves in a variety of cancers, namely, breast cancer, lung cancer, melanoma, and oral squamous cell carcinoma." (PMID 35463335, 2022). "CDK4/6 inhibitors, targeting the direct binding partners of CCND1, show promise for ER+ breast cancer." (PMID 35523804, 2022). "It has been shown that CCND1 suppresses autophagy in mammary epithelium whereas CCND1 inhibits autophagy by activating AMPK in breast cancer cells." (PMID 34445095, 2021). "In fact, cyclin D1 is frequently deregulated in multiple tumor types and overexpressed through copy number variation in over 50% of breast cancer patients." (PMID 33649296, 2021). "A significant difference was observed between OS and disease-free survival (DFS) of patients with breast cancer (n=1746), which indicates that the patients with CCND1 alternations has improved prognosis as compared with those without CCND1 alternations." (PMID 33438725, 2021). "It suggests that the inhibitory effect of α-Mangostin on breast cancer cell migration and invasion is also dependent on the tRXR/Akt/cyclin D1 pathway." (PMID 34539418, 2021). "Cyclin D1 positivity was also detected in the majority (25/30, 83.33%) of breast cancer sections compared with normal breast sections (1/10, 10%)." (PMID 34903946, 2021). "Chrysophanol inhibits proliferation and induces apoptosis through NF-κB/cyclin D1 and NF-κB/Bcl-2 signaling cascade in breast cancer cell lines." (PMID 34519612, 2021). "In breast cancers, oncogenic β-catenin accumulation correlates with cyclin D1 overexpression and both serve as biomarkers for the most aggressive form of the disease." (PMID 34389725, 2021). "In the present study, the impact of CCND1 on survival of patients with breast cancer was investigated using Kaplan–Meier plotter." (PMID 33438725, 2021). "Low expression of CCND1 (0.1761) was found to be correlated with better overall survival (OS) for patients with breast cancer (n=1402)." (PMID 33438725, 2021). "Clinical studies show high expression of Cyclin D1 are often found in aggressive breast cancer, especially TNBC." (PMID 34539418, 2021).
breast cancer (continued). "Previously accumulated data underscore the role of cyclin D1 in the tumorigenesis of mammary cancer." (PMID 33920506, 2021). "Known targets of miR-720 include TWIST1 in breast cancer, Rab35 in cervical cancer, StarD13 in colorectal cancer, and CCND1 in pancreatic cancer." (PMID 33880375, 2021). "The flow cytometry results are in line with our tumorsphere assay data and further indicate the requirement of cyclin D1 for TGFβ to promote stemness in breast cancer." (PMID 33649296, 2021). "Cyclin D1 serves as the major target of bexarotene in several cancer types, such as colon, lung, and breast cancer." (PMID 33491272, 2021). "Immunohistochemical staining of 48 breast cancer tissue samples shed further light on the pathological relevance of ELF5 in the regulation of Cyclin D1 expression in breast cancer." (PMID 33742100, 2021). "However, the underlying mechanism of Cyclin D1 role in breast cancer is still unknown." (PMID 33438725, 2021). "The patient with the most actionable alterations had four actionable alterations, including BRCA loss, CCND1 amplification, PI3KCA base substitutions and the novel ROS1–EPHA7 fusion that was identified in breast cancer tumours for the first time." (PMID 34396843, 2021). "FGFR1 and CCND1 CN alterations were more common in HR + HER2- breast cancer (q = 0.01 and q < 0.001, respectively)." (PMID 33893289, 2021). "Treatment of breast cancer cell lines with the FGFR inhibitor PD 173074 leads to decreased expression of cyclin D1 and a G1 growth arrest, hence, providing rationale for cyclin D1 involvement in resistance to FGFR inhibition." (PMID 34933671, 2021). "In Luminal A and B breast cancer, ER binds to the CCND1 promoter favoring cell proliferative activity." (PMID 34066838, 2021). "Our previous study found upregulation of piR-016658 and downregulation of piR-016975 by cyclin D1 in human breast cancer." (PMID 34295823, 2021). "Conversely, EZH2 knockout can induce G2/M phase arrest of breast cancer and regulate the expressions of cyclin D1 and β-catenin." (PMID 34335707, 2021). "Upregulation of CDK4/6—RB pathway is common in breast cancer, especially in luminal subtypes, where cyclin D1 amplification is identified in 58% of luminal B and 29% of luminal A cancers and CDK4 amplification in 25% and 14%, respectively." (PMID 33530456, 2021). "Overexpression of SOX2 in MCF-7 breast cancer cells has also been shown to increase cell proliferation and tumorigenesis by upregulating cyclin D1 and subsequently facilitating G1/S cell cycle transition." (PMID 34436030, 2021). "Cyclin D1 has been reported for a long time as an E2 target in breast cancer cells which plays a key function in the hormone-dependent promotion of G1/S transition, as confirmed by the increase in cells in the S phase after hormone treatment." (PMID 34678933, 2021). "Conversely, Cdk4 and Cyclin D1 are frequently overexpressed in cancer, with CCND1 amplification present in 20% of breast cancers and CDK4 amplified in 18% of glioblastomas." (PMID 33806417, 2021). "In particular, G1 arrest in breast cancer and hepatocarcinoma cells seems to be related to CCND1 autophagy-induced degradation." (PMID 34445095, 2021). "Maasomi et.al, have evaluated the growth inhibitory effects of SIL and chrysin through regulation of hTERT and cyclin D1 in T47D breast cancer cells." (PMID 34452574, 2021).
breast cancer (continued). "Recent studies have shown that Cyclin D1 is the direct target gene of Jagged1 dependent Notch signaling pathway activation in breast cancer cells, and knockdown of Jagged1 can inhibit cell proliferation by delaying the transition from G1 to S phase." (PMID 33781318, 2021). "Cyclin D1 accumulation is normally tightly regulated, but over-expression of cyclin D1 occurs in almost 50% of human breast cancers." (PMID 34068643, 2021). "A recent research has indicated LINC01355 can inhibit breast cancer growth via transcriptional inhibition of CCND1." (PMID 34355042, 2021). "The same trend of the result was also demonstrated in HT29 colorectal cancer cells, MCF-7 breast cancer cells, and human ovarian cancer cells with downregulation of cyclin D1 and CDK4." (PMID 33507701, 2021). "Paralleling its effects on breast cancer cells, Matrine was also reported to have antitumor properties in other types of cancer through upregulation of let-7b, which inactivates the Wnt/CCND1 signaling pathway and inhibits EMT and lung CSC activities." (PMID 34572067, 2021). "Wnt signaling analysis revealed that Nic treatment downregulated cyclin D1 in all the breast cancer cell types studied." (PMID 34209317, 2021). "Further analysis indicated that there is a significant difference between OS and DFS of patients with breast cancer (n=1746), which indicates that the patients with CCND1 alternations has improved prognosis as compared with those without CCND1 alternations." (PMID 33438725, 2021). "A study documented cyclin D1 gene overexpression and copy number amplification in 20% and 50% of human breast cancer cases, respectively." (PMID 33920506, 2021). "Proliferation, migration, invasion, AKT phosphorylation at Thr308 and Cyclin D1 expression of breast cancer cell lines are enhanced by NUDT5 expression." (PMID 33571243, 2021). "Phosphorylation of AKT at Thr308 and the expression of Cyclin D1 levels were reduced by low NUDT5 expression in 3 breast cancer cell lines." (PMID 33571243, 2021). "We showed that the post‐translational downregulation of CDC6, CDK2, Cyclin D1 and Cyclin D3 is part of the mechanism to reduce breast cancer cell viability." (PMID 33124043, 2021). "We have previously shown that cyclin D1 acts downstream of TGFβ to regulate breast cancer cell migration and invasion, two key features of CSC activity." (PMID 33649296, 2021). "The results of comparison analysis showed that Akt1 and CCND1 (cyclinD1) were significantly different in different types of breast cancer." (PMID 33911067, 2021). "In this study, the expression of β-catenin and Cyclin D1 was evaluated by immunohistochemistry in 82 breast cancer cases." (PMID 34837904, 2021). "It has been found that chrysin/curcumin loaded in PLGA-PEG reduced the expression of cyclin D1 and the proliferation of breast cancer cells." (PMID 33858433, 2021). "Two more recent studies demonstrated that cyclin D1 is specifically degraded during autophagy in hepatocellular carcinoma and breast cancer." (PMID 35008317, 2021). "Akt1 gene expression signature positively correlated with cyclin D1 gene expression signature in different subtypes of breast cancer with highest significance in luminal A, luminal B and basal type." (PMID 34298660, 2021).
breast cancer (continued). "The majority of studies at the cell level found that BCAR3 promotes breast cancer progression through the development of estrogen resistance, promotion of CCND1 expression, promotion of migration and invasion, and regulation of adhesion signaling." (PMID 34707118, 2021). "For instance, ICRT14 inhibited c-Myc and cyclin D1 expression in breast cancer cells as well as it decreased migration and invasion." (PMID 34778043, 2021). "These sequencing data became more robust in the 2000s with the availability of the Cancer Genome Atlas, which elucidated that aberrations leading to hyperactivation of CCND1/CDK4/6 were specifically common in ER+ breast cancer subtypes." (PMID 34771508, 2021). "It has also been described to enhance the expression of cyclin D1 in bovine mammary epithelial cells and luminal A/B breast cancer cells." (PMID 34113576, 2021). "For example, in human breast cancer MDA-MB-231BO cells, hyaluronan activates p38α/β and up-regulates the expression of p21cip1, leading to the decrease of Cyclin D1 level, prolonging the conduction in G0-G1 phase and slowing the growth of breast cancer cells." (PMID 34671218, 2021). "RBMS3 greatly inhibited the protein expression of β-catenin, cyclin D1, and c-Myc in breast cancer cells." (PMID 34804951, 2021). "Auraptene inhibited the proliferation of MDA-MB-231 and MCF-7 human breast cancer cells and significantly inhibited cyclin D1 dose-dependently and delayed tumor progression in rat mammary tumors." (PMID 34239445, 2021). "In 50% of breast cancer patients, cyclin D1 is highly expressed and cyclin D1 is an important marker of cell proliferation." (PMID 33742100, 2021). "Chrysin alone and potentially in combination with metformin decreased cyclin D1 and hTERT gene expression in the T47D breast cancer cell line." (PMID 33858433, 2021). "Subsequently, its dysregulation is also reported in breast cancer and transgenic mice of CCND1 gene also displayed altered mammary cell proliferation and adenocarcinomas." (PMID 33438725, 2021). "Acetylation of ELF5 was found to enhance its ability to inhibit the progression of breast cancer via direct regulation of CCND1 expression." (PMID 33742100, 2021). "Thirdly, cyclin D1 increased phosphorylation of AKTSer 473 in breast cancer cells and animal models, augmented AKT1 activity, which in turn simulates the Warburg effect." (PMID 34631530, 2021). "JAG1 downregulation can induce cell cycle arrest to the G0 \G1 phase by regulating the binding of Notch and cyclin D1 promoter in breast cancer cells." (PMID 33795521, 2021). "Cyclin D1-positive human cancers include mantle cell lymphomas, breast cancers, head and neck carcinomas, oropharyngeal cancers, hepatocellular cancers, colorectal cancers, skin cancers and sarcomas." (PMID 34442137, 2021). "The mean rank level for miRNA-373 and investigated genes, VEGF and cyclin D1, reported a significant increase among primary breast cancer patients followed by benign cases while their expression were the lowest in healthy individual cases (P< 0.0001)." (PMID 34089425, 2021). "Overexpressed cyclin D1 induced Dicer expression in luminal A and basal-like breast cancer subtypes." (PMID 33920506, 2021). "Another study identified that 64 breast cancer cases out of 82 had cyclin D1 gene amplification, and 36 out of 86 cases had cyclin D3 gene amplification." (PMID 33920506, 2021). "The oncogenic properties of Cyclin D1 in breast cancer in particular ER+ invasive ductal carcinoma (IDC) have been established in various studies." (PMID 34394279, 2021).